INS (insulin)
Diseases named in the same sentence as INS in open-access papers (continued):
Sharing a sentence is not in itself a finding about the gene and the disease.
Insulin resistance (continued). "However, the effects of inulin on insulin sensitivity are clear, as inulin supplements can significantly improve insulin resistance in individuals who are obese or overweight." (PMID 39839293, 2024). "Additionally, adipose tissue dysfunction in obesity leads to the release of proinflammatory cytokines such as IL-6 and TNF-α that can directly interfere with insulin signaling within cells, further exacerbating insulin resistance (Fève and Bastard, 2009)." (PMID 39717478, 2024). "BBR has been shown to be effective in improving insulin sensitivity in adipocyte models of insulin resistance, which may depend on reduced methylation and increased expression of hypoxia-inducible factor-3α." (PMID 38957396, 2024). "Anthropometric indices, physical activity, diet, fasting blood sugar (FBS), serum insulin, Homeostatic Model Assessment for Insulin Resistance (HOMA-IR), triglyceride (TG), total cholesterol (TC), low-density lipoprotein-cholesterol (LDL-C), high-density lipoprotein (HDL-C), and PAB were assessed." (PMID 39430281, 2024). "This proinflammatory state can induce insulin resistance, and it is in this insulin-resistant state that the anti-inflammatory effect of insulin is disturbed, while also increasing the concentration of free fatty acids (FFAs), further exacerbating the inflammatory response." (PMID 39011047, 2024). "Moreover, in all subjects, we assessed insulin sensitivity with the homeostatic model assessment for insulin resistance (HOMA)." (PMID 39596226, 2024). "Inflammation can inhibit insulin signaling, contributing to insulin resistance." (PMID 39201413, 2024). "Hypertrophied adipocytes may become insulin-resistant, which intensifies the lipolysis of the fat cells, which contributes to a further increase in hyperinsulinemia/insulin resistance." (PMID 39769002, 2024). "The increased insulin levels observed in these patients may be related to insulin resistance, which triggers cellular stress and tissue dysfunctions that activate inflammatory cascades." (PMID 39518437, 2024). "Additionally, increased O-GlcNAcylation by GlcN treatment attenuated insulin-induced cardioprotection, suggesting a mechanistic link between O-GlcNAcylation and insulin resistance." (PMID 38783961, 2024). "Elevated glucose levels have been shown to disturb autophagy in vitro and in vivo, resulting in the aggravation of diabetes-related metabolic derangements in insulin-target tissues, such as skeletal muscle, which contribute to the worsening of insulin resistance." (PMID 38971910, 2024). "In T2DM model rats, the blood glucose, water intake, urine volume, HbA1c, and homeostasis model assessment-insulin resistance were significantly increased, while the body weight and the insulin level were significantly decreased, indicating the successful establishment of the T2DM model." (PMID 38367173, 2024). "Other mechanisms include increased insulin resistance induced by high-dose glucocorticoids that increases intra-portal insulin, decreases IGFBP-1 that increases free IGF-I, and direct glucocorticoid effects in increasing hepatic IGF-I synthesis and decreasing hepatic insulin clearance." (PMID 39665021, 2024). "We utilised two publicly available datasets to identify changes in the mitochondrial proteome that may contribute to insulin resistance in adipocytes, one of the primary targets for insulin." (PMID 38960128, 2024). "The current study aims to investigate the pharmacological effects of single-atom Ce-N-C nanozyme (SACe-N-C) on the improvement of insulin resistance and to elucidate its underlying mechanisms using HFD/STZ-induced C57BL/6J mice and insulin-resistant HepG2 cells." (PMID 39334959, 2024). "However, insulin response (AUC) remained stable during the 2-year maintenance period, whereas insulin resistance (HOMA-IR) significantly decreased (p < 0.05)." (PMID 38732623, 2024).
Insulin resistance (continued). "Indeed, studies have established a negative correlation between plasma beta-carotene levels and insulin resistance, as well as a positive correlation with plasma adiponectin levels, suggesting a beneficial impact of beta-carotene on insulin sensitivity." (PMID 39275338, 2024). "Insulin resistance (IR) is characterized by hyperglycemia due to the failure of insulin-dependent cells, such as hepatocytes, myocytes, and adipocytes, to properly respond to normal concentrations of circulating insulin, the major glucose-lowering hormone." (PMID 38892230, 2024). "Additionally, miR-19 and let-7 play a role in insulin signal transduction and have been related to the development of type 2 diabetes and obesity-induced insulin resistance." (PMID 38542682, 2024). "Furthermore, PPARα contributes to the amelioration of insulin resistance by reducing the dysregulation of intracellular insulin signaling cascade and protein expression." (PMID 38276548, 2024). "It affects insulin release and promotes insulin resistance in people with type 2 diabetes." (PMID 39687080, 2024). "Strong evidence was established only for reductions in fasting insulin and insulin resistance." (PMID 39064705, 2024). "This involves feeding animals a HFD to induce hyperinsulinemia and insulin resistance, followed by an injection of a low dose of STZ to slowly reduce pancreatic β cell mass, leading to a decrease in insulin production and mimicking the pathophysiology associated with T2DM in human." (PMID 38444587, 2024). "Lower snacking quality was associated with higher cardiometabolic blood markers including fasting TG (mmol/L) (β; – 0.02, P = 0.02), postprandial TG (6hiAUC mmol/l/s; β; – 400, P = 0.01), insulin (mU/L) (β; – 0.15, P = 0.04) and insulin resistance (HOMA-IR; β; – 0.04, P = 0.04))." (PMID 37709944, 2024). "Ostarine has been shown to reduce the secretion of leptin and adiponectin from white adipocytes, while low levels of leptin can intensify de novo lipogenesis in the liver and promote lipid accumulation in muscles, affecting insulin production in the pancreas and contribute to insulin resistance." (PMID 38059982, 2024). "Background and Objectives: In this study, the effects of an eight-week exercise and nutrition program on blood lipids, glucose, insulin, insulin resistance (HOMA-IR), leptin, ghrelin, irisin, malondialdehyde (MDA), and Growth Differentiation Factor 15 (GDF15) in overweight women were investigated." (PMID 39768899, 2024). "Non-G-allele carriers showed greater reductions in fasting insulin, insulin resistance, total cholesterol, LDL cholesterol, and triglycerides compared to G-allele carriers." (PMID 39125390, 2024). "mTORC1 activation enhances insulin resistance in the main insulin-target organs." (PMID 39261960, 2024). "The different degrees of insulin resistance and insulin levels might therefore explain the altered endothelial function in T2DM compared with T1DM." (PMID 39037711, 2024). "However, GLUT4 overexpression can alter insulin sensitivity and kinase activities in an insulin resistance context, which limits its use in studies involving genetic or pharmacological manipulation with endogenous GLUT4." (PMID 39749015, 2024). "Moreover, IMD administration significantly decreased FBG, fasting serum insulin levels, insulin resistance, serum triglycerides, and LDL-C levels, and it increased the serum HDL-C levels of rats." (PMID 39338366, 2024). "It enhances insulin sensitivity by promoting the storage of fatty acids in adipose tissue, thereby preventing ectopic fat deposition in other tissues like the liver and muscle, which can lead to insulin resistance." (PMID 39767130, 2024). "Notably, we found significant positive correlations between plasma GFAP levels and C-peptide at baseline, as well as insulin and insulin resistance, after 3 months in our study." (PMID 39275164, 2024).
Insulin resistance (continued). "The levels of insulin signaling proteins (IRS1Tyr612, IRS1Ser307, AKTSer473, GSK3βSer9, AMPKαThr172, and mTORSer2448) were measured to observe the antidiabetic effect on the alleviation of insulin resistance." (PMID 39795155, 2024). "Indeed, pregnancy is known to stimulate an increase in the number and function of beta cells to adapt to insulin resistance, leading to elevated insulin secretion." (PMID 38626157, 2024). "Reactive oxygen species trigger stress-related kinases, like c-Jun N-terminal kinase as well as p38 mitogen-activated protein kinase, which can stimulate the phosphorylation of serine residues in IRs, that suppresses the insulin signaling pathway, retaining ongoing the system of insulin resistance." (PMID 38921683, 2024). "We hypothesised that increasing BCAA catabolism would upregulate insulin-stimulated glucose transport and attenuate insulin resistance induced by BCKA." (PMID 39464407, 2024). "Fasting insulin of 261.5 pmol/l indicates insulin resistance." (PMID 38461278, 2024). "Furthermore, insulin alleviated LPS‐induced insulin resistance, enhanced glucose uptake in the hippocampus, and promoted the Pentose Phosphate Pathway (PPP) and nicotinamide adenine dinucleotide phosphate (NADPH) production." (PMID 39073013, 2024). "Moreover, supplementing with 15 g of inulin per day for 6 months resulted in a reduction in fasting insulin levels and an improvement in the homeostatic model assessment for insulin resistance (HOMA-IR) in patients with prediabetes." (PMID 39458444, 2024). "Insulin resistance and faulty insulin production are hallmarks of the pathogenesis of T2DM." (PMID 39063997, 2024). "The dysregulation of the insulin signaling pathway in insulin-dependent tissues such as skeletal muscle and adipose tissue is of critical importance in the development of insulin resistance and blood glucose homeostasis in GDM and T2DM, as outlined in many previous reports." (PMID 39684804, 2024). "ROS negatively affects insulin signaling and contributes to the development of insulin resistance." (PMID 38612580, 2024). "Moreover, the obese cohort had lower insulin sensitivity indices and disposition indices, which indicates reduced beta cell function in insulin resistance compared to the normal-weight and RYGB cohort." (PMID 39203840, 2024). "In addition, with aging and age-associated metabolic dysfunctions such as obesity or peripheral insulin resistance, neurons lose their sensitivity to insulin as well." (PMID 39408862, 2024). "Additionally, insulin resistance is characterized by diminished biological reactions to insulin stimuli within target tissues such as the liver, muscles, and adipose tissue." (PMID 39595541, 2024). "Firstly, vitamin D may increase insulin secretion and improve insulin resistance by directly acting on pancreatic beta cells, promoting their function and proliferation." (PMID 39744244, 2024). "In addition, SCFAs promote insulin secretion and sensitivity while also reducing energy intake and insulin resistance." (PMID 39451562, 2024). "Because excess fructose has been associated with reduced insulin sensitivity, we examined the effect of fructose with and without insulin resistance on glycolytic metabolism." (PMID 38892515, 2024). "In addition, most PCOS patients have impaired glucose tolerance (OGTT) due to insulin resistance and elevated insulin, so we further performed an OGTT test." (PMID 38195648, 2024). "The observation of improvement of insulin resistance and protection of islets and insulin secretion after treatment with antibodies against SeP suggests that targeting this protein may be a new approach to treat MASLD and various metabolic disorders." (PMID 39409124, 2024).
Insulin resistance (continued). "The results of the other study exhibited that probiotic intake in TLR2−/− mice by increasing lipopolysaccharides and then TLR/JNK pathway activation resulted in downregulating insulin signaling pathway and inducing insulin resistance in the liver and muscle tissue of animals." (PMID 38504163, 2024). "Obese cows tend to have lower postpartum insulin concentrations and more severe insulin resistance." (PMID 39881718, 2024). "This is likely because early adolescence and puberty are characterized by a temporary decrease in insulin sensitivity and an increase in insulin resistance, which can affect lipid metabolism and lead to increased blood cholesterol and TG, as well as decreased HDL-C levels." (PMID 38999917, 2024). "The best evidence that our model could be used to mimic the pathophysiology of T2D in humans is that the diet induced insulin resistance disappeared after the bariatric surgery exactly like in morbidly obese insulin resistant human patients." (PMID 38702370, 2024). "Insulin resistance appears to contribute to the underlying pathophysiology of PCOS, and indeed, many of the sequelae of PCOS can be improved by interventions that reduce insulin levels." (PMID 38524210, 2024). "Insulin resistance was improved by reducing plasma glucose levels and α-amylase and glucosidase activity, increasing glucose transport, decreasing serum insulin levels, and enhancing insulin sensitivity as well as improving beta-cell function." (PMID 38675719, 2024). "This may potentially cause persistent activation of the mammalian target of rapamycin complex 1 (mTORC1), which leads to decreased insulin signaling and contributes to the development of insulin resistance." (PMID 38427692, 2024). "A 2-h SJL has been reported to increase the risk of prediabetes and type 2 diabetes by approximately twofold and to be associated with impaired glucose homeostasis, increased fasting plasma insulin concentrations, and insulin resistance, thus affecting glucose tolerance." (PMID 39300989, 2024). "The dysregulation of such genes not only affects insulin signaling but also influences cellular redox balance and inflammatory responses within the pancreatic islets, potentially exacerbating β-cell dysfunction and insulin resistance." (PMID 39926598, 2024). "Elevated insulin levels, stemming from insulin resistance and β-cell dysfunction, may enhance the renal reabsorption of uric acid." (PMID 39191722, 2024). "Consequently, studying insulin and insulin resistance becomes a crucial avenue for exploring the comorbidity of AD and T2DM." (PMID 38379904, 2024). "However, a high-fat diet is known to increase pancreatic β-cell mass by both hypertrophy and hyperplasia to produce more insulin as a compensatory mechanism against insulin resistance." (PMID 38414818, 2024). "Also, ROS can disrupt insulin signaling pathways, leading to insulin resistance, which is a precursor to type 2 diabetes." (PMID 39765836, 2024). "Additionally, moxibustion also exhibited effects in lowering FBG, testosterone, and fasting insulin levels, which are key biochemical indicators associated with PCOS and insulin resistance." (PMID 38665877, 2024). "High insulin levels, up to a certain point, may reflect insulin resistance, which could have a detrimental effect on BMD." (PMID 38731059, 2024). "Brain insulin resistance, as proposed by Arnold’s study, indicates that insulin receptors are expressed in various cell types in the brain, with most insulin in the cerebrospinal fluid originating from circulating pancreatic insulin." (PMID 38977983, 2024). "However, β-cell function, insulin sensitivity, and insulin resistance remained significantly different in FGFR1m participants even after controlling for these adiposity indices." (PMID 38957656, 2024). "Furthermore, reducing insulin-induced dilation and blood flow are characteristic features of insulin resistance-related morbidities such as T2DM and obesity." (PMID 39610878, 2024).
Insulin resistance (continued). "Based on these findings, we proposed the hypothesis that hyperglycemia-mediated FoxO6 plays a pivotal role in hindering insulin signaling, subsequently prompting the induction of gluconeogenesis-related genes in conditions marked by insulin resistance." (PMID 38441531, 2024). "The disease may be characterized by failure of insulin secretion or insulin resistance or both; may progress either rapidly or slowly and may be mild or severe." (PMID 38805513, 2024). "Also we demonstrated that older Brazilian children with ASD have higher values for triglycerides, insulin levels, free fatty acids, and the HOMA-index indicating a higher risk for insulin resistance." (PMID 39595815, 2024). "This genotype effect on weight loss diminished after adjustment for changes in fasting insulin or HOMA-IR, suggesting that improvement in insulin resistance may influence weight loss." (PMID 39064800, 2024). "T2DM is characterized by relative insulin deficiency or insulin resistance, in which the muscles and organs, such as the liver, are not sensitive enough to insulin so that blood glucose cannot be used effectively and remains at a high level." (PMID 39598478, 2024). "In addition, fasting plasma glucose and insulin, as well as insulin resistance, diminished significantly after 3 months, an effect that persisted at 6 months." (PMID 39064705, 2024). "Thus, we demonstrated that the ST method protected the HFD-fed female OVX mice from insulin resistance by increasing peripheral and hepatic insulin sensitivity." (PMID 38791103, 2024). "Though costlier and more challenging, utilizing methods like HOMA-IR and insulin clamp for insulin resistance measurement could enhance study accuracy." (PMID 39765929, 2024). "Notably, a correlation emerged between factors of glucose metabolism and insulin resistance (glucose, insulin, HbA1C, HOMA-IR), with SHBG (β: −0.108) at the initial assessment being negatively associated with depressive symptomatology in the CDI." (PMID 39519542, 2024). "Reduced insulin sensitivity commonly leads to insulin resistance." (PMID 39062577, 2024). "Finally, alterations in fatty acid metabolism and lipid accumulation within insulin-sensitive tissues are thought to contribute to insulin resistance as well." (PMID 38791018, 2024). "Additionally, a significant proportion of women with PCOS have insulin resistance, manifesting in heightened insulin levels." (PMID 38256276, 2024). "Moreover, leptin is known to inhibit insulin secretion and plays a significant role in insulin resistance in obesity and type 2 DM." (PMID 38707092, 2024). "In humans, an increased CB chemosensitivity was also assessed by the Dejours test, which measures the decrease in basal ventilation produced by 100%O2, which was significantly higher in the prediabetes population and correlated with insulin resistance and fasting insulin levels." (PMID 38646610, 2024). "Reduced insulin sensitivity and elevated concentrations are the main features of insulin resistance, which may increase AIP levels as well as cholesterol saturation in bile, thereby promoting gallstone formation." (PMID 38509591, 2024). "Conversely, other studies suggest that chronic hyperglycemia and dysregulated insulin signaling impair autophagic flux, leading to the accumulation of dysfunctional cellular components and contributing to the pathogenesis of insulin resistance and β-cell dysfunction." (PMID 38971910, 2024). "Improving insulin sensitivity is a key goal in managing insulin resistance and type 2 diabetes." (PMID 38397886, 2024). "Similarly to insulin and insulin resistance, C-peptide values increased during the development of pregnancy in all three examined groups in our study, which is why neither C-peptide nor insulin proved to be good predictive markers of GDM." (PMID 39452932, 2024).